MRPS30 (mitochondrial ribosomal protein S30)
Synonyms: MRP-S30; S30mt; PDCD9; PAP; mL65
Tractability: Small molecule: a structure with a bound ligand is known. PROTAC: ubiquitination databases record sites on it; its protein half-life has been measured.
Gene: Protein-coding gene on chromosome 5 (44,808,947 to 44,820,428, forward strand). Ensembl gene ENSG00000112996.
Subcellular location: Mitochondrion
Pathways (Reactome):
Metabolism of proteins: Mitochondrial ribosome-associated quality control; Mitochondrial translation elongation; Mitochondrial translation initiation; Mitochondrial translation termination
Gene Ontology:
Molecular function: RNA binding; structural constituent of ribosome
Biological process: apoptotic process; mitochondrial translation; translation
Cellular component: mitochondrial large ribosomal subunit; mitochondrion; mitochondrial inner membrane; ribosome
Genetic constraint (gnomAD): Loss-of-function variants: 41 observed, 42.79 expected, observed/expected ratio (o/e) 0.96, 90% interval 0.75 to 1.24. The upper end of that interval is the gene's LOEUF score, 1.24, which puts it in group 5 of 6, group 1 being the genes least tolerant of losing a copy. Missense variants: 588 observed, 553.4 expected, observed/expected ratio (o/e) 1.06, 90% interval 0.99 to 1.14. Synonymous variants: 258 observed, 227.52 expected, observed/expected ratio (o/e) 1.13, 90% interval 1.02 to 1.26.
Homologues: Orthologues: chimpanzee MRPS30 (99% identical), macaque MRPS30 (89% identical), pig MRPS30 (81% identical), rabbit MRPS30 (80% identical), dog MRPS30 (80% identical), guinea pig MRPS30 (79% identical), mouse Mrps30 (74% identical), rat Mrps30 (73% identical), tropical clawed frog mrps30 (53% identical), zebrafish mrps30 (46% identical), Drosophila melanogaster mRpS30 (26% identical), Caenorhabditis elegans mrps-30 (23% identical).
Diseases named in the same sentence as MRPS30 in open-access papers:
MRPS30 is named in the same sentence as 22 diseases in open-access papers, as found by Europe PMC text mining. Sharing a sentence is not in itself a finding about the gene and the disease. The quoted sentences say what the papers report.
breast carcinoma (14 papers, 2009 to 2025). "MRPS30 is also known as programmed cell death 9 (PDCD9) with a role in breast cancer susceptibility." (PMID 34306039, 2021). "The minor g-allele of signal 1 SNP rs10941679 conferred a 15% increased risk of ER+ breast cancer and higher expression levels of the MRPS30 and FGF10 genes and was the most strongly associated SNP with MRPS30 expression in this 1 Mb region." (PMID 27640304, 2016). "Simultaneous consideration of overall association and intervention interaction point to genomic regions in the vicinity of FGFR2 and MRPS30 genes as relevant to breast cancer risk among postmenopausal women." (PMID 21702935, 2011). "The polymorphism rs10941679 near HCN1/MRPS30 was also associated with percent dense area; women who were homozygous for the G allele (previously associated with increased breast cancer risk) had 4% to 5% lower densities than women with at least one A allele." (PMID 19232126, 2009). "Recent research has proposed hypotheses about the MRPS30 genomic region and its relation to postmenopausal breast cancer risk." (PMID 38136890, 2023). "SNP in tumor suppressor MRPS30 was associated with advancement of breast cancer, but SNP in this gene may be responsible for pathogenesis of EOC." (PMID 30970615, 2019). "In pathway enrichment analysis for up regulated genes, genes such as RPLP0 and MRPS30 were associated with pathogenesis of many cancer types such as gastric cancer and breast cancer, but these genes may be responsible for advancement of GBM." (PMID 31137733, 2019). "The 10q26.13/FGFR2 rs10736303 (proxy of rs2981579), 5p15.2/ROPN1L rs1092913, 5q12/MRPS30 rs7716600, and 8q24.21 rs1562430 were also confirmed to be associated with breast cancer risk, although the magnitude of the last three SNPs was smaller than that of previous reports." (PMID 22452962, 2012). "Combined main effect and intervention interaction analyses raise novel hypotheses concerning the MRPS30 genomic region and the effects of hormonal and dietary exposures on postmenopausal breast cancer risk." (PMID 21702935, 2011). "MRPS30 is dysregulated in many types of cancer, including breast cancer, CRC, lung cancer, and gastric cancer." (PMID 39859078, 2025). "This solution was also enriched in genes known to be associated with breast cancer susceptibility (BLM, CASP8, CASP10, DNAJC1, FGFR2, MRPS30, and SLC4A7, P-value = 3 × 10−4)." (PMID 33735170, 2021). "FGF10 is an oncogene that binds to FGFR2 and is overexpressed in ∼10% of human breast cancers, whereas MRPS30 plays a key role in apoptosis." (PMID 27640304, 2016). "The counterparts of these fusion proteins, such as MRPS30 and PDE4DIP, may also be associated with an increased risk for breast cancer and leptomeningeal disease progression, respectively." (PMID 31480474, 2019). "HCN1 is adjacent to other genes that may be related to breast cancer risk including FGF10 and MRPS30, and is just outside a region linked to mammographic density." (PMID 19232126, 2009). "Connections in the OXPHOS pathway included the hub gene Mrps30, which when downregulated, suppresses OXPHOS to promote breast cancer growth." (PMID 36980301, 2023). "In fact, both SConES GS and GM selected chromosome regions related to breast cancer, like 3p24 (SLC4A7/NEK10), 5p12 (FGF10, MRPS30), 10q26 (FGFR2), and 16q12 (TOX3)." (PMID 33735170, 2021). "These assays showed that the PRE containing SNP1 frequently interacted with the FGF10 and MRPS30 promoter regions in MCF7 and BT474 breast cancer cell lines, but only with MRPS30 in the MDA-MB-361, MDA-MB-231, and Bre80 cell lines." (PMID 27640304, 2016). "It is interesting that MRPS30 is not expressed in normal breast luminal epithelial cells but is significantly upregulated in breast cancer patients, a phenomenon which contradicts its role in promoting apoptosis." (PMID 39859078, 2025).
breast carcinoma (continued). "Six of these genes (MRPS30, SETD9, ADGRV1, ZNF703, PRR33, and PSG4) showed different directions of association with breast cancer in epithelial vs. stromal (nonepithelial) cells." (PMID 36690614, 2023). "Genome-wide association studies (GWAS) have identified breast cancer susceptibility loci in or near genes such as FGFR2, TOX3 (formerly known as TNRC9), LSP1, HCN1/MRPS30, MAP3K1 and at 2q that had not previously been considered." (PMID 19232126, 2009).
breast tumors (3 papers, 2016 to 2024). "Based on the significant increase in the expression of MRPS30 in breast tumor tissues and breast cancer cells in our in vitro studies, in agreement with previous studies, the role of this gene in breast cancer can be confirmed." (PMID 38886335, 2024). "According to various studies, MRPS30 is a pro‐apoptotic gene, so significantly increased expression of this gene in breast tumor tissues and cells might indicate resistance of the cells to these conditions." (PMID 38886335, 2024). "Because MRPS30 is a pro‐apoptotic gene, its increased expression in breast tumor tissues and cells might indicate cell resistance to these conditions." (PMID 38886335, 2024).
lung carcinoma (3 papers, 2022 to 2025). "For instance, ETV1 is associated with prostate cancer; RFX3-AS1, MRPS30, MRPS30-DT, and MIR3201 are associated with breast cancer; MIR548H4, AATF, and APCDD1L-DT are associated with lung cancer." (PMID 40440618, 2025). "LncRNA MRPS30 divergent transcript (also known as BRCAT54) is recently reported to promote lung cancer." (PMID 35191803, 2022). "Long non-coding RNA (lncRNA) MRPS30 divergent transcript (also known as BRCAT54) is recently reported to promote lung cancer." (PMID 35191803, 2022). "BRCAT54 (also known as MRPS30 divergent transcript) is an anti-tumor long non-coding RNA (lncRNA) in lung cancer, while its role in vestibular schwannoma (VS) is unclear." (PMID 35137654, 2022). "BRCAT54 (also known as MRPS30 divergent transcript) is an anti-tumor lncRNA in lung cancer." (PMID 35137654, 2022).
infiltrating ductal carcinomas (2 papers, 2013 to 2019). "MRPS30 is not expressed in normal breast luminal epithelial cells but is upregulated in infiltrating ductal carcinomas." (PMID 31788446, 2019). "In addition, some studies have showed that MRPS30 is not expressed in normal breast luminal epithelial cells, but it is up-regulated in infiltrating ductal carcinomas." (PMID 24039999, 2013).
triple-negative breast carcinoma (2 papers, 2022 to 2025). An invasive breast carcinoma which is negative for expression of estrogen receptor (ER), progesterone receptor (PR), and human epidermal growth factor receptor 2 (HER2). "MRPS30 is highly expressed in vestibular schwannomas and triple-negative breast cancers and promotes tumor progression." (PMID 39913623, 2025).
Coma (1 paper, 2024). The complete absence of wakefulness and consciousness, which is evident through a lack of response to any form of external stimuli. "Increased expression of MRPS30 was predicted to be a risk factor for retinopathy, neuropathy, and coma in T2DM patients." (PMID 39280009, 2024).
deafness (1 paper, 2023). An inherited or acquired condition characterized by the complete loss of the ability to hear from one or both ears. "Mitochondrial ribosomal protein (MRP) genes, including MRPS30, have been linked to human diseases such as deafness and retinitis pigmentosa." (PMID 38136890, 2023).
invasive breast carcinoma (1 paper, 2012). A carcinoma that infiltrates the breast parenchyma. "Most recently, replication of two index SNPs: rs3803662 at 16q12.2/TOX3 and rs10941679 at 5p12 near MRPS30 involving 7,800 African American women (including 316 women with incident invasive breast cancer) have also been established." (PMID 22778704, 2012).
lactic acidosis (1 paper, 2014). Metabolic acidosis characterized by the accumulation of lactate in the body. "Known mutations in MRPs are associated with lactic acidosis, organ dysfunction, and early death, and several MRPs (MRPS29, MRPS30) have been implicated in apoptosis." (PMID 25410281, 2014).
leukemia (1 paper, 2025). A malignant (clonal) hematologic disorder, involving hematopoietic stem cells and characterized by the presence of primitive or atypical myeloid or lymphoid cells in the bone marrow and the blood. "Additionally, BTG1 and MRPS30, whose inactivation has been linked to venetoclax resistance in leukemia cell lines, exhibited decreased expression." (PMID 40709247, 2025).
non-small cell lung carcinoma (1 paper, 2025). A group of at least three distinct histological types of lung cancer, including non-small cell squamous cell carcinoma, adenocarcinoma, and large cell carcinoma. "The long non-coding RNA divergent transcript of MRPS30 can interact with RPS9, inhibit JAK-STAT signaling, and inhibit the progression of non-small cell lung cancer." (PMID 39913623, 2025).
prostate carcinoma (1 paper, 2023). A carcinoma that arises from epithelial cells of the prostate gland. "MRPS30, an apoptosis-related gene, exhibited differential expression between androgen-resistant and androgen-responsive prostate cancer cell lines." (PMID 38136890, 2023).
thyroid cancer (1 paper, 2025). "Our results showed that both MRPL13 and CLPX are highly associated with the ribosome signaling pathway, while MRPS30 is highly correlated with the thyroid cancer signaling pathway and showed high expression." (PMID 39913623, 2025).
tumor (6 papers, 2010 to 2025). "For example, MRPL41 and MRPS30 are under expressed in renal clear cell carcinoma (p < 0.01), which may be associated with tumor heterogeneity, but requires further investigation." (PMID 35719986, 2022). "For further analysis of melanotic tumor formation process, we focused our attention on 5 genes that induced melanotic mass to high frequency and might represent different classes of melanotic tumor suppressor genes: cct2, cul4, hyx, mRpS30 and ush." (PMID 20540764, 2010).
cancer (4 papers, 2012 to 2019). A tumor composed of atypical neoplastic, often pleomorphic cells that invade other tissues. "Therefore, it is possible that rs4415084 might be a proxy for other potentially functional SNPs, such as rs3761648, that influence MRPS30 expression and in consequence the cancer risk." (PMID 24039999, 2013). "However, additional genes linked to cancer processes were found deregulated in this study including AHRR, C7, CLPTM1L, and MRPS30 involved in apoptosis, CDH6 in cell adhesion and CEP72 in the cell cycle." (PMID 22412903, 2012).
MRPS30 also shares sentences with these, for which no sentence is quoted: gastric cancer (2 papers); Vestibular schwannoma (2); bovine tuberculosis (1); lymphoma (1); neuropathy (1); retinitis pigmentosa (1); retinopathy (1).